GFAP (glial fibrillary acidic protein)
Diseases named in the same sentence as GFAP in open-access papers (continued):
Sharing a sentence is not in itself a finding about the gene and the disease.
ischemia (continued). "Pyknotic cell nuclei, terminal deoxynucleotidyl transferase dUTP nick end labeling (TUNEL)-positive cells, and glial fibrillary acidic protein mRNA expression were increased in ischemia, suggesting injury." (PMID 20300568, 2010). "GFAP mRNA expression levels were higher in the neuroretinas from ischemia-reperfusion eyes than from sham-operated eyes and increased gradually with increasing duration of reperfusion." (PMID 20300568, 2010). "Within hours of ischemia onset, astrocytes upregulate GFAP reactivity." (PMID 41002405, 2025). "It was suggested that increased co-expression of GFAP and Nestin in the cortex following focal ischemia might indicate reversion to an immature cell state, potentially reflecting astrocyte reprogramming towards neuronal differentiation." (PMID 39851520, 2025). "We counted GFAP+cells; the control and sham groups showed few GFAP+reactive cells, whereas, in the ischemia group, the number was 25 cells by field on average; in just the ischemia+NanoPSO or preNanoPSO+ischemia groups, the number of GFAP+reactive cells decreased by 75% (p < 0.0001)." (PMID 39594495, 2024). "Interestingly, ischemia-induced increases in GFAP signal intensity were blocked by FA, whereas FA-induced increased IL-6 intensity in these ganglia." (PMID 38147796, 2024). "Vimentin and GFAP are both intermediate filaments and are well known to be upregulated in Müller cells and astrocytes in general in the CNS as a response to stress, for instance, ischemia." (PMID 37175625, 2023). "To evaluate whether astrogliosis is induced by these insoluble TDP-43 inclusions in the ischemia model, we further determined the expression levels of the glia marker, GFAP." (PMID 36614118, 2022). "The initial decrease followed by an increase in GFAP expression was also observed in hippocampal astrocytes in a model of transient global ischemia, and may reflect astrocyte dysfunction and reactivity secondary to fluctuations in oxygen levels." (PMID 36672545, 2022). "However, the HBO-PC combined with proteasome inhibitor resulted in post-ischemic changes of GFAP expression that were similar to those after the ischemia alone." (PMID 35250819, 2022). "Thus, GFAP expression has been used to inspect the morphological changes during astrogliosis following ischemia." (PMID 33629276, 2021). "Additionally, propranolol was found to reduce TNFα and GFAP protein, among other inflammatory markers, in a rat model of ischemia." (PMID 34563566, 2021). "In addition, GFAP/Vimentin double-knockout mice showed reduced cortical blood flow in the brain and greater lesions following local ischemia." (PMID 33922467, 2021). "Furthermore, KLF4 expression always strongly co-localized with cells expressing high levels of GFAP in the ischemic penumbra at days 2 and 7 post-ischemia, especially at day 7, but this co-localization was markedly disrupted in the ischemic core." (PMID 32264912, 2020). "In addition, we used western blot 24 h after reperfusion to measure the protein expression of Iba1 and GFAP in the ischemia penumbra, which reflects the activation of microglia and astrocytes, respectively." (PMID 32917229, 2020). "Also, GFAP-positive cells were enhanced in ischemia group (80%±3.16) compared with the sham group (P<0.001)." (PMID 32963745, 2020). "In the 50 and 100 mg/kg YES-10/ischemia groups, the distribution pattern of GFAP immunoreactive astrocytes in the CA1 field was similar to that in the vehicle/ischemia group, and their ROD was about 191% and 190%, respectively, of that in the vehicle/sham group." (PMID 31991860, 2020). "Moreover, the previous findings have indicated that GFAP is up-regulated by reactive astrocytes in several neurodegenerative situations, like ischemia, and for this reason it is abundantly used as an alternative indicator of brain damage after ischemia." (PMID 32963745, 2020).
ischemia (continued). "The increased myeloperoxidase (MPO) activity and expression of TNF-α, iNOS, and glial fibrillary acidic protein (GFAP) during ischemia could also be abrogated by eriodictyol." (PMID 31814878, 2019). "In the ischemia operated group, the morphology of GFAP+ astrocytes was slightly changed after tgCI." (PMID 30781368, 2019). "Ischemia-slow rewarming was associated with a significant overall reduction in numbers of GFAP-positive astrocytes in all white matter regions compared to ischemia-normothermia, while the ischemia-48 h and ischemia-72 h hypothermia groups remained significantly higher than sham control (P < 0.05)." (PMID 31300687, 2019). "Furthermore, previous evidences have shown that reactive astrocytes upregulate GFAP in many neurodegenerative conditions such as ischemia." (PMID 31231488, 2019). "GFAP promoter-controlled IL-15 expressing transgenic mice showed enlarged brain infarcts, exacerbated neuronal deficits following rose bengal induced cerebral cortical photothrombotic ischemia." (PMID 31291966, 2019). "In the ischemia operated group, GFAP+ astrocytes started to show morphological change." (PMID 30781368, 2019). "However, at 5 days after TGCI in the ischemia groups, GFAP-immunoreactive astrocytes were activated (altered), namely, they had a bulky cytoplasm with thickened processes as reactive astrocyte form." (PMID 31627311, 2019). "Also, the rate of GFAP-positive cells was higher in ischemia group (58.4% ± 5.3) than the sham (P<0.001)." (PMID 31231488, 2019). "Additionally, GFAP/Vimentin double knockout mice showed enhanced cortical cerebral blood flow reduction and larger lesions after focal ischemia." (PMID 31291966, 2019). "Furthermore, the number of hypertrophic GFAP+ cells was significantly increased from 7 days after ischemia, and the number persisted until 21 days after ischemia in rats." (PMID 30781368, 2019). "However, GFAP+ cells dramatically increased at day 2, reached the peak level at day 7, and gradually dropped down to day 28 post-ischemia." (PMID 30524246, 2018). "However, post-ischemia melatonin administration was able to decrease significantly GFAP levels in both right (p < 0.01) and left hippocampus (p < 0.05)." (PMID 30029514, 2018). "A trend to an increase in GFAP+ staining area could also be noted in these animals, but it was weaker as in the ischemia group." (PMID 28800629, 2017). "Both CAI and ischemia individually enhanced astrocytic (GFAP-positive) activation." (PMID 27418952, 2016). "This increase of contractility may exacerbate retinal damage after ischemia, as seen by the increase of GFAP and vimentin along with decreased retinal function 72 hours post ischemia." (PMID 27322388, 2016). "In the Tat-Atox1 protein treated ischaemia group, few GFAP-immunoreactive astrocytes featuring abnormal thorn-shaped bodies and cytoplasm were found while the remaining astrocytes had a thread-like morphology with thorn-shaped bodies and a small amount of cytoplasm." (PMID 25781353, 2015). "Also, GFAP immunoreactivity was a little lower in the 20 mg/kg ASA-DA-ischemia-group at 5 days post-ischemia compared with that in the vehicle-ischemia-group." (PMID 24073226, 2013). "In this study, GFAP-expressing cells increased compared with those of the control group following cerebral anoxia and ischemia, which indicates that GFAP may be involved in the recovery of HIBD." (PMID 23408790, 2013). "However, GFAP+ astrocytes became reactive form and their immunoreactivity was increased in the vehicle-ischemia-group at 5 days post-ischemia compared with that in the vehicle-sham-group." (PMID 24073226, 2013). "Signs of glial activation in transgenic retinas became more manifest with time: elevated expression of GFAP in the inner parts of the retina and of nestin on P30 indicates the presence of either ischemia and/or mechanical forces exerting traction on the retina." (PMID 22880002, 2012).
ischemia (continued). "Importantly, these BrdU+cells expressed distinct antigens – NF-200 only in the layer vulnerable to ischemia, and GFAP in the entire CA1- in pyramidal layer as well as in strata oriens and radiatum." (PMID 21799862, 2011). "However, the individual Zn administration increased GFAP expression after ischemia." (PMID 38707461, 2024). "Interestingly, the trained animals showed an increase in the GFAP expression 3 days after 2VO, which could be explained by acrobatic training modulation and the ischemia in parallel." (PMID 38939055, 2024). "ADEV GFAP may dynamically reflect changes during the first month post-ischemia." (PMID 38891912, 2024). "An increase in GFAP occurs when intermediate filaments are upregulated in Müller cells in response to stress and this has previously been reported in inherited retinal degeneration, chronic retinal diseases, as well as retinal trauma induced by ischemia or laser damage." (PMID 36430950, 2022). "Notably, Om-PDRN (20 mg) injection at pain site alleviated mechanical allodynia and reduced glial fibrillary acidic protein (GFAP) expression, which is predominantly associated with neuro-inflammatory states, on spinal nerve ligation (SNL)- and chronic post-ischemia-induced pain models." (PMID 34067499, 2021). "However, in the 200 mg/kg YES-10/ischemia group, the cytoplasm of GFAP immunoreactive astrocytes was lesser hypertrophied compared to those in the other ischemia groups, and their ROD was significantly lower (about 109% versus vehicle/sham group) than that in the vehicle/ischemia group." (PMID 31991860, 2020). "Since astrocytes and microglia are the main immune cells that quickly respond following ischemia and participate in the neuroinflammation, next, we performed double immunofluorescent analysis of dsDNA with cell type‐specific markers for microglia (Iba1) and astrocytes (GFAP)." (PMID 32239625, 2020). "However, in the vehicle/ischemia group, GFAP immunoreactive astrocytes were altered." (PMID 31991860, 2020). "In order to investigate whether these proliferating NSCs could differentiate into mature neurons or astrocytes, and also, if they will show beneficial or detrimental effects to the ischemia injured brain, BrdU double labeling of the cells with either NeuN or GFAP was performed." (PMID 31733648, 2019). "Moreover, maslinic acid treatment promoted the expression of GLT-1 and GFAP post-ischemia." (PMID 27548129, 2016). "Extracellular K+ measurements during the induction of terminal ischemia/anoxia revealed a faster and steeper rise of extracellular K+ in GFAP/EGFP/α-Syn−/− mice, which might suggest altered K+ clearance, presumably due to changes in the ability of astrocytes to take up K+." (PMID 25426721, 2014). "Moreover, serum lactate levels during ischemia were positively associated with the severity of WMI as measured by GFAP (p < 0.0001; LME) and Iba1 (not shown; p < 0.0001; LME)." (PMID 24416093, 2013). "Confirmation of these results in alternative drug- or ischemia-induced ALF models as well as in age- and sex-randomized studies is essential for establishing GFAP as a new innovative biomarker for liver injury-related brain parameters." (PMID 38606159, 2024). "The current study demonstrated that GFAP expression was used to demonstrate SGC activation in various models of traumatic nerve injury as well as in models of type 1 diabetes, ischemia, facial cancer, chemotherapy administration, and peripheral inflammation." (PMID 35336044, 2022). "The levels of GFAP protein/astrocytes increased significantly in OGD exposed slices, indicating that astrocytes, although fewer in number, were activated 24 h after ischemia." (PMID 36292998, 2022). "In fact, GFAP is an indicator of neuroinflammation in the CNS25 and it is also involved in the progression of neurodegeneration in ischemia, AD, MS, Amyotrophic Lateral Sclerosis (ALS) and PD26–28." (PMID 35810203, 2022).
ischemia (continued). "The activity-stress rats have been observed increased significantly GFAP-immunoreactive cells in the hippocampal CA3 region, which is similar to the response found in ischemia." (PMID 34565419, 2021). "And RQKL decreased expression level of GFAP and IBA-1 compared to ischemia group, indicating RQKL inhibited activation of astrocyte and microglia." (PMID 32457601, 2020). "Hypothermia treatment significantly reduced the ischemia-induced reactive astrocytosis and microgliosis in the hippocampal CA1 region, but GFAP and Iba-1 immunoreactivity was significantly increased in the hippocampal CA1 region compared to the CTL group." (PMID 32531881, 2020). "In the 10 mg/kg LA/ischemia group, the distribution and relative optical density (ROD) of GFAP immunoreactive astrocytes were similar to those in the vehicle/ischemia group, that is, the ROD was 236% of the vehicle/sham group." (PMID 31940961, 2020). "We also measured the expression of the astrocyte marker GFAP and pro-inflammatory factor TNF-α in the ischemia penumbra 24 h after reperfusion." (PMID 32917229, 2020). "At day 7 post-ischemia, when DCX+ neurons were first observed after the injury, we focused on comparison of transcriptions of the genes in the striatum of both GFAP-CreER:Rbp-Jfl/fl mice and the Rbp-Jfl/fl." (PMID 30524246, 2018). "Investigating ischemia-related tissue damage based on the NVU concept, these regions were quantitatively analyzed for alterations of collagen IV, GFAP and Iba." (PMID 28445478, 2017). "In order to identify the cell types of non-pyramidal ID1+ and ID4+ cells, double immunofluorescence staining was performed for ID1/GAD67, ID4/GFAP and ID4/Iba-1 in the hippocampal CA1 region at 5 days post-ischemia." (PMID 25503067, 2015). "We examined this in situ in the isolated intact optic nerve from GFAP-EGFP mice aged P8-12, using the oxygen-glucose deprivation (OGD) model of ischemia." (PMID 26189008, 2015). "Recent studies have shown that ischemia increases the extracellular ATP released by damaged cells, which stimulates astrocytic P2Y1, resulting in high GFAP expression." (PMID 23890321, 2013). "Double-immunofluorescent labelling of brain slices from rats 24 h post-ischemia confirmed that these STI-1-expressing cells included Neu-N+ neurons, GFAP+ glia, MAP-2+ neurons and vWF+ vascular endothelial cells." (PMID 23836498, 2013). "Reactive astrocytes are earmarked by increased expression of S100B and glial fibrillary acidic protein (GFAP), appear around 24 hours after the onset of ischemia, and undergo hypertrophy and hyperplasia for a period of weeks thereafter." (PMID 20862385, 2010). "Moreover, shRNA-Ptbp1 treatment mitigated OGD-induced increases in PTBP1 and the astrocyte activation marker GFAP, indicating the crucial role of PTBP1 in astrocyte dysfunction following ischemia." (PMID 41328340, 2026). "While GFAP-positive astrocytes become particularly prominent in the CA1 region, a significant increase in their number in the CA3 region occurs only after severe ischemia." (PMID 41602964, 2026). "While GFAP immunosignals were increased already by 24 h after ischemia and did not further increase by 72 h of ischemia, the number of Iba1-positive morphologically activated microglia only increased by 72 h of ischemia." (PMID 39272984, 2024). "We also found an increase in GFAP staining following CA/CPR (Sham: 3.227% ± 0.2149% vs. CA/CPR: 12.74% ± 2.303%, p = 0.0021), suggesting astrocytes remain persistently activated at subacute timepoints after ischemia." (PMID 40822706, 2024). "Notably, the cytotoxic effect of glutamate on astrocytes was completely overturned by treatment with EDAC, which increased the morphological complexity and overall GFAP-EGFP fluorescence, and an equivalent effect of EDAC was observed in ischemia." (PMID 37170258, 2023).
ischemia (continued). "After induction of unilateral focal cortical ischemia in the rat brain, MannR was found to be highly expressed in GFAP-positive cells in the lesioned side, but not in the non-lesioned one." (PMID 36782185, 2023). "Furthermore, rTMS is reported to induce a upregulation of GFAP and IBA1 immunoreactivity in a gerbil model of ischemia, when magnetic stimulation was initiated immediately after ischemic injury." (PMID 32915781, 2020). "Finally, to verify that the activation of microglia and astrocytes were initiated by TLR4 and NF-κB respectively, we investigated the colocalization of GFAP and P-NF-κB and the colocalization of Iba1 and TLR4 in the ischemia penumbra." (PMID 32917229, 2020). "Elevated levels of lactate in the CSF as well as elevated levels of neurone-specific enolase (NSE), glial fibrillary acidic protein (GFAP), and S100B in CSF and serum have been assessed as promising biomarkers to monitor acute spinal cord damage due to ischemia." (PMID 32098337, 2020). "However, the two-way ANOVA test indicated that ischemia and PDD diets significantly increased the GFAP (df = 2, F = 5.341, p = 0.0093) and Iba-1 immunoreactivity (df = 2, F = 19.06, p < 0.0001)." (PMID 32759679, 2020). "Then, we injected a mixture of the Lv‐GFAP‐EGFP and Lv‐Pax6 or Lv‐mCherry into the ipsilateral striatum of rats 7 days before MCAO and sacrificed the rats 14 days after the induction of ischemia to assess the effects of exogenous PAX6 on ischemia‐induced astrocyte‐to‐neuron conversion." (PMID 29451327, 2018). "Although Müller glial cells in normal rat retinae express little or no GFAP, they showed increased GFAP expression in retinal injuries including ischemia and glaucoma; this expression occurs within the first 24 hours." (PMID 29176876, 2017). "In the present study, treatment with PEDF resulted in attenuated up-regulation of collagen IV in subcortical regions affected by ischemia, while GFAP and Iba were not affected." (PMID 28445478, 2017). "Similarly, the global transient BCCAO-induced ischemia was accompanied by increased GFAP expression 7 days later, and CBD at 30 mg/kg reduced the GFAP expression." (PMID 28788104, 2017). "To define the contribution of hypoxemia to the severity of WMI, we analyzed the association between the CaO2, measured just before the end ischemia, and the magnitude of WMI, as measured by GFAP and Iba1 (not shown)." (PMID 24416093, 2013). "The expression of GFAP, GLAST or vimentin together with a passive current pattern and dye-coupling in a large subpopulation of EGFP+ cells evidenced that polydendrocytes can give rise to reactive astrocytes after ischemia." (PMID 22590616, 2012). "Indeed, brain injury following trauma or peri-traumatic ischemia increases the concentration of specific biomarkers, such as S100β protein, neuronal-specific enolase (NSE), ubiquitin C-terminal hydrolase-L1 (UCH-L1), and glial fibrillary acidic protein (GFAP)." (PMID 31547411, 2019). "However, bothSutherlandia and elderberry diets did not attenuate GFAP immunoreactivity as compared withthe ischemia group on the control diet." (PMID 25324465, 2014). "Given that the association between HSPA8 and Iba-1 was weaker than that of HSPA8 and GFAP immunoreactivity cells, especially after 12 h of reperfusion, we emphasize that HSPA8 of the spinal astrocyte might play an essential role in the pathogenesis of ischemia and reperfusion injury." (PMID 34362408, 2021). "After cerebral ischemia, astrocytes were strikingly activated with increased expression of GFAP, however the treatment of His 1000 had no further effect on the activation of astrocytes on 7 d after ischemia, nor did His 1000–0 and 1000–500 treatments on 14 d after ischemia (n = 6–7)." (PMID 26481857, 2015).